MMP9 (matrix metallopeptidase 9)
Diseases named in the same sentence as MMP9 in open-access papers (continued):
Sharing a sentence is not in itself a finding about the gene and the disease.
nephronophthisis (1 paper, 2023). Progressive tubulointerstitial injury, inherited in an autosomal recessive pattern, caused by mutations in genes involved in ciliary function, which may result in an end stage renal failure. "Indeed, we observed a boost of MMP9 enzymatic activity in this model of nephronophthisis, and a ~40-fold increase of periostin mRNA by RT-qPCR." (PMID 38039285, 2023).
neural tumours (1 paper, 2014). "Furthermore, Wnt-induced gelatinase B/MMP-9 expression has been implicated in embryonic neural stem cells proliferation in conditions of hypoxia, a similar mechanism may, therefore, regulate cancer stem cells proliferation within neural tumours." (PMID 24473089, 2014).
NK/T cell lymphoma (1 paper, 2007). "The strong expression of MMP-9 is uniquely characteristic of nasal NK/T cell lymphoma and may contribute to its strong tendency to disseminatate and the extensive necrosis which is always seen." (PMID 18093334, 2007). "MMP-9 can be also responsible for chemoresistance of NK/T-cell lymphoma." (PMID 18093334, 2007). "Sixteen of the 19 patients with nasal NK/T cell lymphoma expressed MMP-9." (PMID 18093334, 2007). "In contrast, only 8 of the 22 patients with nasal non-NK/T cell lymphoma expressed MMP-9." (PMID 18093334, 2007). "Thus, the strong expression of MMP-9 in nasal NK/T cell lymphoma may explain its strong tendency to metastasize." (PMID 18093334, 2007).
non-melanoma skin carcinoma (1 paper, 2018). "MMP-9-induced damage to the collagenous matrix of the skin is one of the hallmarks of photoaging and non-melanoma skin cancer." (PMID 30429790, 2018).
normal-tension glaucoma (1 paper, 2007). "Also of note is that MMP9 was found to be upregulated at both the mRNA and protein level in mononuclear blood cells of normal-tension glaucoma patients." (PMID 17293780, 2007).
occupational asthma (1 paper, 2015). Asthma attacks caused, triggered, or exacerbated by OCCUPATIONAL EXPOSURE. "Specific allergen challenge is also able to induce changes in MMPs and TIMPs, in particular MMP-9, in occupational asthma." (PMID 26770019, 2015).
odontogenic cyst (1 paper, 2020). A cyst in the jaw that arises from tissues of tooth development. "MMP-9 may have an important role in the angiogenesis of odontogenic cysts." (PMID 32467797, 2020).
opioid dependence (1 paper, 2025). "During the intoxication stage, MMP-9 concentrations in individuals with alcohol and opioid dependence are similar and higher than in the control group." (PMID 39997037, 2025). "In the intoxication phase, MMP-9 levels in patients with alcohol and opioid dependence are very similar and elevated compared to the control group." (PMID 39997037, 2025).
opioid use disorder (1 paper, 2018). A substance-related disorder that involves the recurring use of opioids despite negative consequences. "We analyzed catalase (CAT), glutathione (GSH), malondialdehyde (MDA), superoxide dismutase (SOD) activity (as oxidative markers) and also MMP-9 and TNF-α level in the plasma of patients with opioid use disorder during two weeks of methadone therapy." (PMID 29892317, 2018).
opisthorchiasis (1 paper, 2022). Infection with flukes of the genus Opisthorchis. "During the progression of chronic opisthorchiasis, the number of Mmp2+, Mmp9+, and TIMP1+ cells in the liver of infected hamsters significantly increased." (PMID 36355906, 2022).
oral submucous fibrosis (1 paper, 2025). "In contrast, in our study on naringenin's antifibrotic effects in oral submucous fibrosis (OSMF) focuses on molecular targets such as MMP2, MMP3, MMP9, TGFB1, ESR1, and SERPINE1, which are crucial in ECM remodeling and inflammation." (PMID 40575446, 2025).
oropharyngeal tumour (1 paper, 2014). "Samples from 61 patients diagnosed with oropharyngeal tumour were studied by immunohistochemistry against MMP-2, MMP-7, MMP-9 and MMP-13." (PMID 26019601, 2014).
osteomyelitis (1 paper, 2023). An acute or chronic inflammation of the bone and its structures due to infection with pyogenic bacteria. "Inhibition of MMP9 can suppress the LPS-induced NF-κB signaling pathway, reducing osteoclast formation and expression of pro-inflammatory cytokines and slowing down the development of osteomyelitis." (PMID 37904457, 2023).
Ovarian cyst (1 paper, 2024). The presence of one or more cysts of the ovary. "Consistent with our findings, MMP9 is overexpressed in PCOS, closely associated with ovarian cyst formation and follicular atrophy, and its expression can be modulated by pharmacological treatment, underscoring its significant role in the pathophysiology of PCOS." (PMID 39850756, 2024).
ovarian serous cystadenocarcinoma (1 paper, 2022). A malignant serous cystic epithelial neoplasm arising from the ovary. "The positive correlation between HK2 and CDH2, fibronectin, MMP9, ZEB1, ZEB2 and vimentin in OV (ovarian serous cystadenocarcinoma) was confirmed by using TIMER 2.0." (PMID 35953860, 2022).
penile carcinoma (1 paper, 2015). "Campos and colleagues, using the conventional, subjective expression ‘scoring’ technique, have suggested that two members of the MMP family (MMP2 and MMP9) are over-expressed in penile carcinoma." (PMID 25901368, 2015).
perennial allergic rhinitis (1 paper, 2009). Allergic rhinitis caused by indoor allergens and lasting year round. "Studies of MMP-9 have not demonstrated any elevation in perennial allergic rhinitis;47 however, 3 to 10 hours after exposure to nasal allergens, the eosinophilic cationic protein (ECP) and MMP-9 are elevated." (PMID 19488576, 2009).
periapical abscess (1 paper, 2021). "Significant higher expression of CYP4F3 (P < 0.0001), VEGF (P < 0.0001), MMP-9 (P < 0.001), IL-8 (P < 0.0001), and TLR2 (P < 0.0001) were noted in the periapical abscess compared with healthy controls." (PMID 34539639, 2021). "CYP4F3, VEGF, MMP-9, IL-8, and TLR2 represented the most upregulated genes in periapical abscess." (PMID 34539639, 2021).
peripheral T-cell lymphomas (1 paper, 2007). "Five of 8 (63%) of peripheral T-cell lymphomas, unspecified expressed MMP9 and 4 of 4 (100%) of peripheral T-cell lymphomas, unspecified expressed MMP9." (PMID 18093334, 2007).
pilomatricoma (1 paper, 2024). "In patients with bullous pilomatricoma, MMP-2- and MMP-9-positive cells had higher H-scores than those in patients with ordinary pilomatricoma." (PMID 38350760, 2024).
pituitary apoplexy (1 paper, 2022). A rare, potentially life-threatening disorder caused by acute ischemic infarction or hemorrhage in the pituitary gland. "No evident correlation was found between expression levels of MMP9, MMP2, TIMP2, and PTTG1 and clinical features of PAs, including gender, age, compression symptoms, pituitary apoplexy, tumor texture, resection degree, and recurrence." (PMID 36052250, 2022).
pneumococcal pneumonia (1 paper, 2013). A febrile disease caused by STREPTOCOCCUS PNEUMONIAE. "Notably, the expression levels of MMP-9 in the infected lungs were significantly decreased after depletion of DCs suggesting the involvement of DCs in MMP-9 production during pneumococcal pneumonia." (PMID 23802100, 2013).
promyelocytic leukemia (1 paper, 2013). "Additionally, the expression of MMP9 by human promyelocytic leukemia HL-60 cell line has been associated with intercellular adhesion molecule-1 (ICAM-1) shedding into the cell medium, which would suggest another explanation." (PMID 24086377, 2013).
Proptosis (1 paper, 2024). An eye that is protruding anterior to the plane of the face to a greater extent than is typical. "As to OSD, MMP-9 concentrations were not related to the diagnosis of DED but were positively correlated with proptosis in patients with inactive TED in a chronic and fibrotic phase." (PMID 39259164, 2024).
Pseudoxanthoma elasticum (1 paper, 2009). "It is noteworthy to highlight that both mRNA and protein of ABCC6, causative of the pseudoxanthoma elasticum, have been identified in leukocytes, macrophages, and lymphocytes, and that all these white blood cells abundantly contain MMP-9." (PMID 19828023, 2009). "This commentary discusses a study on measurements of matrix metalloproteinase 9 (MMP-9) in serum of pseudoxanthoma elasticum patients recently published in Journal of Molecular Medicine." (PMID 19828023, 2009). "The authors concluded that the measurement of serum MMP-2 and MMP-9 could be applied for non-invasive monitoring of matrix-degradative processes in pseudoxanthoma elasticum." (PMID 19828023, 2009). "Furthermore, the potential difference in leukocyte counts and profiles between patients affected by pseudoxanthoma elasticum and healthy subjects may significantly affect the release from white blood cells and platelets during clotting and subsequent recovery in serum of MMP-9." (PMID 19828023, 2009).
psoriatic arthritis (1 paper, 2021). Joint inflammation associated with psoriasis. "Interestingly, Lindqvist and coworkers found an increase and displacement of MMP9 when comparing normal skin from healthy individuals and psoriatic skin of a methotrexate-treated patient with polyarthritic psoriatic arthritis." (PMID 34715781, 2021).
pulmonary sarcoidosis (1 paper, 2025). Sarcoidosis affecting the lung parenchyma. "Therefore, the downregulation of MMP9 in the PBMCs from patients with pulmonary sarcoidosis with EPL might indicate the different pathobiological features between extrapulmonary and pulmonary sarcoidosis." (PMID 41463010, 2025).
pyoderma gangrenosum (1 paper, 2020). An idiopathic, rapidly evolving, and severely debilitating disease occurring most commonly in association with chronic ulcerative colitis. "Pyoderma gangrenosum and PASH HS lesions also exhibit overexpression of MMP-2 and MMP-9." (PMID 32973741, 2020).
radiodermatitis (1 paper, 2021). A cutaneous inflammatory reaction occurring as a result of exposure to biologically effective levels of ionizing radiation. "The endpoints were radiodermatitis scale, histological analysis HE, Picrius Sirius and the gene expression of interleukin-10 (IL-10) and matrix metalloproteinase-9 (MMP-9)." (PMID 33656099, 2021).
rectal carcinoid tumors (1 paper, 2015). "Because MMP-9 is known to play a pivotal role in regulating invasiveness in various human cancers, miR-885-5p may increase for inhibiting tumor cell invasion via MMP-9 in rectal carcinoid tumors." (PMID 26090613, 2015).
relapsing (1 paper, 2022). "A previous study exploring the role of MMPs in several neuromuscular conditions before and after IVIG treatment showed that baseline elevated levels of MMP-9 dropped after IVIG, while a post-treatment increase in MMP-2 levels could indicate a relapsing disease." (PMID 36358365, 2022).
renal adenocarcinoma (1 paper, 2023). "This study shows that the curcuminoid EF24 in combination with TRAIL increases peroxidase activity in the renal adenocarcinoma cell line ACHN, reducing the level of intracellular H2O2 and MMP-2/MMP-9 activity, a mechanism that is also observed after treatment with curcumin and TRAIL." (PMID 36674555, 2023).
Renal atrophy (1 paper, 2023). Atrophy of the kidney. "Previous studies have identified MMP9 as a DEG in IF/TA patients, and Fn1 was identified as a DEG in a study employing an animal model of renal atrophy or allograft damage." (PMID 37623492, 2023).
renal cyst (1 paper, 2023). A fluid filled sac in the kidney. "Surprisingly, while increased level of protein expression or enzymatic activity is demonstrated in human serum, in human cystic tissue and in culture media of cells from rodent models of ADPKD, the role of MMP9 in cystic kidney disease is still not elucidated." (PMID 38039285, 2023).
restrictive lung disease (1 paper, 2017). "MMP-9 involves wide-ranging extracellular matrix remodeling, and facilitates inflammatory cell trafficking that contribute to pathological progresses of restrictive lung disease and pulmonary dysfunction in newborn babies." (PMID 28747201, 2017).
retinal detachment (1 paper, 2020). An eye emergency condition which may lead to blindness if left untreated. "Previous study has also shown that upregulation of Zn2+ can increase the activity of MMP9 in retinal detachment models." (PMID 32562453, 2020).
retinal edema (1 paper, 2012). "MMP-9 levels in the vitreous proteome varied with the level of SRF but not retinal edema." (PMID 22773904, 2012).
retinal vein occlusion (1 paper, 2020). An occlusion of the retinal vein. "The AH concentrations of MMP-1, MMP-2, MMP-7, and MMP-9 are also elevated in patients with retinal vein occlusion." (PMID 32596291, 2020).
rhegmatogenous retinal detachment (1 paper, 2012). Retinal detachment secondary to retinal tear or break. "Recent reports have found that levels of MMP-9 in SRF and vitreous correlate with the extent and duration of rhegmatogenous retinal detachment." (PMID 22773904, 2012).
salmonellosis (1 paper, 2014). Infections with bacteria of the genus salmonella. "This study motivates the development of therapeutic interventions directed against this Lcn2-dependent, MMP-9-driven tissue degradation pathway to combat salmonellosis." (PMID 24465207, 2014).
scoliosis (1 paper, 2021). A congenital or acquired spinal deformity characterized by lateral curvature of the spine. "Interestingly, the genetic interaction between MMP9 and FMRP also occurs in nonneuronal tissues, which might explain the nonneuronal symptoms of FRAXA patients, such as JHM, the hallmark characterizing hEDS, and some orthopedic features (e.g., flat foot and scoliosis)." (PMID 34831458, 2021).
scrapie (1 paper, 2025). A fatal disease of the nervous system in sheep and goats, characterized by pruritus, debility, and locomotor incoordination. "In detail, the expression levels of CD10, cathepsin B, cathepsin D, and MMP9-40 kDa were upregulated in ME7 scrapie-infected mice." (PMID 40302732, 2025). "However, MMP9-90 kDa was downregulated in ME7 scrapie-infected mice." (PMID 40302732, 2025). "We observed an abnormal accumulation of proteolytic stress-related proteins, including CD10, cathepsin B, cathepsin D, and matrix metalloproteinase 9 (MMP9), in the brains of ME7 scrapie-infected mice and sporadic CJD patients." (PMID 40302732, 2025). "In conclusion, we identified abnormal accumulation of proteolytic stress-related proteins, including CD10, cathepsin B, cathepsin D, and MMP9, in the brains of ME7 scrapie-infected mice and sporadic CJD patients." (PMID 40302732, 2025). "Similar to the western blotting results in ME7 scrapie-infected mice, the expression levels of CD10, cathepsin B, cathepsin D, and MMP9-40 kDa were upregulated in sporadic CJD patients." (PMID 40302732, 2025). "Notably, proteolytic stress-related proteins, including CD10, cathepsin B, cathepsin D, and matrix metalloproteinase 9 (MMP9), showed altered expression patterns in ME7 scrapie-infected mice compared to matched controls." (PMID 40302732, 2025). "Notably, proteolytic stress-related proteins, including CD10, cathepsin B, cathepsin D, and MMP9, were also upregulated in the cerebral cortex and caudate putamen of ME7 scrapie-infected mice compared to matched controls." (PMID 40302732, 2025).
seborrheic dermatitis (1 paper, 2025). A chronic, inflammatory skin disorder that affects the scalp, central face and skin folds; it is characterized by scaling and itching. "The ELISA analysis revealed that miRNA transfection significantly modulated IL-6, MMP-9, and TNF-α expression levels compared to the control condition, highlighting their therapeutic potential for seborrheic dermatitis." (PMID 40227405, 2025).
sensitization (1 paper, 2023). "In the context of nerve sensitization, MMP-9 can mask opioid analgesia, without interfering with opioid-induced hyperalgesia." (PMID 36830637, 2023).
skin abscess (1 paper, 2019). "We confirmed that MMP-9 is also abundant in a skin abscess, and, similar to findings for a kidney abscess, MMP-9 is more abundant in infected tissue than in control tissue." (PMID 31040245, 2019). "We hypothesized that the host protease MMP-9 is important for liberation of nutrients from host proteins that allow for S. aureus proliferation within a skin abscess." (PMID 31040245, 2019).
skin infection (1 paper, 2019). An inflammatory process affecting the skin, caused by bacteria, viruses, parasites, or fungi. "The previous data showed that the host protease MMP-9, as well as the staphylococcal proteases Aur and SspB, have the ability to degrade collagen, an abundant host protein that is present at the site of S. aureus skin infections." (PMID 31040245, 2019).
skin reaction (1 paper, 2022). "Luteolin and quercetin may be the core active ingredients of QYSLS in the treatment of EGFRI-related adverse skin reactions, and their therapeutic effects are potentially mediated through PTGS2, CCL2, and MMP9 in the IL-17 and TNF signaling pathway." (PMID 35372072, 2022).
Sleep apnea (1 paper, 2023). An intermittent cessation of airflow at the mouth and nose during sleep is known as sleep apnea. "Interestingly, leptin and ischemia-reperfusion injury (i.e., typical of sleep apnea) have been shown to regulate the expression of matrix metalloproteinase-9 (MMP-9)." (PMID 36380123, 2023).
sleep disorder (1 paper, 2022). A change from the patient's baseline sleeping pattern, in the hours slept and/or an alteration/dysfunction in the stages of sleep. "The levels of MMP3 and MMP9 can be used to evaluate sleep disorders and cognitive function in PD patients, respectively." (PMID 36072482, 2022).
Sorsby fundus dystrophy (1 paper, 2022). A rare progressive autosomal dominant macular dystrophy, presenting between the third and sixth decades of life, characterized by retinal atrophy and retinal detachment and leading to loss of central vision, then peripheral vision, and eventually blindness. "A notable MMP9 partner is TIMP3, which we and others have shown to be linked with AMD as well as with Sorsby fundus dystrophy." (PMID 36498929, 2022).
spinal meningioma (1 paper, 2015). Spinal meningioma isa rare type of spinal cord cancer. "They concluded that, in spinal meningiomas, high MMP-9 expression seems to be associated with the development of recurrences only in the absence of PR expression." (PMID 25821815, 2015).
spinal muscular atrophy (1 paper, 2025). A motor neuron disease that affect the muscles, and characterized by muscle weakness and atrophy resulting from progressive degeneration and irreversible loss of the anterior horn cells in the spinal cord (i.e., lower motor neurons) and the brain stem nuclei. "Schoser and colleagues, using immunohistochemistry on muscle biopsies from a small cohort (n = 5) of patients with ALS, spinal muscular atrophy, and chronic axonal neuropathies, observed strong MMP-9 immunoreactivity—and to a lesser extent, MMP-2 and MMP-7—in all samples." (PMID 41009467, 2025).
Spontaneous pneumothorax (1 paper, 2020). Pneumothorax occurring without traumatic injury to the chest or lung. "The serum expressions of TIMP-1 and MMP-9 in 80 COPD patients complicated with spontaneous pneumothorax (COPD group) and 52 healthy volunteers (control group) were detected by ELISA." (PMID 32063958, 2020). "In summary, the expression of MMP-9 and TIMP-1 in COPD patients with spontaneous pneumothorax was higher than that in normal controls, but the expression was not correlated with arterial blood gas parameters." (PMID 32063958, 2020).
sporadic CJD (1 paper, 2025). "However, MMP9-90 kDa was downregulated in sporadic CJD patients." (PMID 40302732, 2025).
staphylococcal infection (1 paper, 2024). An infection caused by Staphylococcus. "Elevated plasma levels of MMP9 in STAT3-deficient patients and its role in degradation of extracellular matrix during tissue remodeling led us to hypothesize that MMP9 may be differentially expressed in myeloid STAT3-deficient as compared with WT mice during pulmonary staphylococcal infection." (PMID 37982695, 2024).